TNF (tumor necrosis factor)
Diseases named in the same sentence as TNF in open-access papers (continued):
Sharing a sentence is not in itself a finding about the gene and the disease.
Sepsis (continued). "In clinical trials, supplementation of 200 mg/day of CoQ10 significantly reduced TNF-α inflammatory marker, and improved survival in sepsis patients, demonstrating its potential as an adjunct therapy in managing infections." (PMID 39599909, 2024). "Macrophages and neutrophils play crucial roles in the inflammatory response during sepsis, secreting inflammatory mediators such as TNF-α and IL-1β to enhance the inflammatory response." (PMID 39455728, 2024). "Constitutive activation of the vagus nerve after CLP in mice blocked the release of TNF-α and was incompetent to the second LPS challenge, and the α7 nicotinic acetylcholine receptor plays an important role in sepsis neural regulation." (PMID 39040114, 2024). "Early intervention to block the signaling pathways responsible for inflammatory transmission and inhibition and neutralization of TNF-α have significant implications for the management of sepsis in clinical individuals." (PMID 39252831, 2024). "The mean TNF-α concentration in sepsis was increased approximately 10-fold compared to the mean concentration in healthy participants." (PMID 38558800, 2024). "Histone H3 lysine 9 dimethylation in late sepsis inactivates the promoter of TNF and IL-1β transcription, downregulating immune sensitivity to endotoxin stimulation." (PMID 39040114, 2024). "TNF-α, IL-1β and IL-6 are pro-inflammatory cytokines that play a central role in the pathogenesis of sepsis." (PMID 39885929, 2024). "Lymphopenia is observed in sepsis mainly due to apoptosis accelerated by tumor necrosis factor (TNF)-alpha and interleukin (IL)-1, and is independently predictive of bacteremia." (PMID 38395788, 2024). "Administration of anti-PD-L1 antibodies prevented sepsis-induced monocyte dysfunction and decreased TNF-α, IL-6, and IL-10 production at different stages of sepsis, implying an overall reduction in systemic inflammation." (PMID 37776443, 2024). "And the relative abundance of Bacteroides in the lung microbiome was significantly correlated with serum TNF-α concentrations, a key mediator of the septic stress response that predicts sepsis patient mortality." (PMID 39176264, 2024). "While early cytokine responses can be protective against microbial infections, excessive cytokine production (e.g., TNF) can contribute to the pathogenesis of sepsis and septic shock." (PMID 39763679, 2024). "The concentrations of IL-1β (p < 0.001), IL-6 (p < 0.001), and TNF-α (p < 0.001) were significantly elevated in the liver in the Tac1+/+ mice following CLP-surgery-induced sepsis compared with the sham-operated controls." (PMID 38539834, 2024). "IFN-gamma is a key inflammatory mediator in the establishment of sepsis and has been shown to work in synergy with TNF-alpha to induce a cytokine storm." (PMID 38817614, 2024). "H. sampsonii has been reported to play an anti‐inflammatory role by inhibiting the secretion of inflammatory factors such as TNF‐α and IL‐6 in mice with LPS‐induced sepsis." (PMID 39312269, 2024). "This upregulation of AQP4 can be attenuated by dexamethasone, primarily through tumour necrosis factor alpha (TNF-α) regulation, although the use of corticosteroids in sepsis remains controversial and is recommended under certain conditions." (PMID 39544938, 2024). "We proved that Fen and Melo significantly alleviated severe inflammation and reduced TNF-α, IL-1β, and IL-6 production in LPS-induced sepsis models, thus warranting further exploration of their role in sepsis clinical treatment." (PMID 39628572, 2024). "Another study showed that cardiac tissue TNF-α and IL-6 levels were significantly lower in the ghrelin-treated group compared to the sepsis model group." (PMID 39144689, 2024). "In a retrospective RCT subgroup analysis, showing no survival benefit of anti-TNFα Ab CB0006 in 80 unselected severe sepsis patients, the patients with increased entry TNF-levels appeared to benefit from the high dose anti-TNF Ab (survival rate 86%, n = 7)." (PMID 38807151, 2024).
Sepsis (continued). "Epalrestat, a commercial ARI, was employed as an intervention in a rat sepsis model, demonstrating significant reductions in inflammatory factors TNF-α, IL-1β and IL-6." (PMID 38188141, 2024). "Sepsis is an uncontrolled systemic inflammatory response; inflammatory mediators such as TNF-α and IL-6 are elevated in sepsis, and it has been described that ER stress is dramatically induced in sepsis." (PMID 38672256, 2024). "TNF-α, IL-1β and IL-6 belong to the most important systemic pro-inflammatory factors undergoing activation at the onset of sepsis." (PMID 39497013, 2024). "Clinical sepsis is known to involve the release and propagation of circulating proinflammatory cytokines, including TNF, early in the septic process." (PMID 39469706, 2024). "The findings of our study are in agreement with the results of some others in this field, for example, it has been reported that in many inflammatory diseases such as sepsis, TNF-a, IL-1b and IL-6 serum levels increase significantly." (PMID 38952770, 2024). "This ameliorated septic response in CQ/LPS-injected mice was further emphasized by the significant reduction of serum and peritoneal lavage fluid TNF-α levels, which is a key marker of sepsis." (PMID 39701924, 2024). "This study reports a significantly lower TNFα production after LPS challenge in patients with sepsis and bacteremia than in healthy volunteers and patients undergoing elective cardiac surgery." (PMID 39559359, 2024). "Protection against severe sepsis was confirmed with the observation that TNF-α, IL-1β, IL-6, LDH, ALT and urea levels were decreased to almost basal levels in MFX-treated mice 24 h after CLP compared to untreated mice." (PMID 39200042, 2024). "This intervention resulted in reduced levels of biochemical organ injury markers and inflammatory cytokines (IL-6, IL-10, and TNF-α), indicating attenuation of the sepsis-induced inflammatory response." (PMID 38888975, 2024). "The intensification of P2X7R expression and activation subsequent to sepsis triggers the production of pro-inflammatory cytokines (IL-1β and TNF-α), thereby inducing tissue damage." (PMID 38546748, 2024). "Curcumin was found to improve survival and regulate proinflammatory cytokines (TNF-α, IL-6 and IL-1β) and anti-inflammatory cytokines (IL-2 and IL-10) in mice with sepsis/ALI induced by CLP." (PMID 39051370, 2024). "In the CLP group, there was a significant elevation in both IL-1β and TNF-α levels compared to the control group, reflecting the pronounced inflammatory response induced by sepsis (p < 0.001)." (PMID 38326366, 2024). "In this study, we will provide a detailed analysis of the production of IL-6 and TNF-α by preterm and term newborns at birth in response to different stimuli, such as various sepsis-related bacteria and TLR ligands." (PMID 38562936, 2024). "IL-1β, IL-6, and TNF-α are common inflammatory factors that reflect the body’s inflammation levels, changing in response to infections, sepsis, or other inflammatory triggers." (PMID 39247187, 2024). "Macrophages are essential to the pathophysiology of sepsis, as they secrete various pro-inflammatory factors such as TNF-α, IL-1, IL-6, and reactive nitrogen and oxygen species, which are crucial for fighting pathogens and tumors." (PMID 39337575, 2024). "Those exosomes showed better clinical outcomes compared to preexisting TNF-α or IL6 biologic inhibitors in mouse models of sepsis, experimental autoimmune encephalomyelitis and inflammatory bowel disease." (PMID 38838263, 2024). "In sepsis, systemic inflammation marked by elevated cytokines like IL-6 and TNF-α impairs erythropoiesis, leading to increased RDW, which correlates with disease severity and poor outcomes." (PMID 39844844, 2024). "When macrophages release excessive amounts of pro-inflammatory cytokines such as TNF-α, IL-1, and IL-6 in an uncontrolled manner, it can lead to a severe inflammatory response known as a cytokine storm, which can progress to severe sepsis." (PMID 39337575, 2024).
Sepsis (continued). "The formation of ROS is enhanced by proinflammatory cytokines, such as interleukin-6 (IL-6) and tumor necrosis factor-alpha (TNF-α), contributing to organ harm associated with sepsis." (PMID 38629103, 2024). "In our study, we observed in mice that CLP-induced sepsis resulted in decreased survival, increased release of the pro-inflammatory cytokines IL-1β, IL-18, and TNF-α, and cardiac dysfunction." (PMID 38584827, 2024). "In sepsis, the most extensively studied cytokines are TNF-α and IL-1, which can activate target cells and stimulate the production of additional cytokines." (PMID 39252831, 2024). "Certain lncRNAs can modulate inflammatory variables including IL-6 and TNF-α, impacting the course of sepsis." (PMID 39735547, 2024). "Our study found that the level of serum IL-6 and TNF-α of sepsis mice was observed greatly upregulated at hyperinflammatory state and then dramatically downregulated at immunosuppressive state." (PMID 37776443, 2024). "It activates MyD88 then NF‐κB and finally releases inflammatory cytokines including TNF‐α, interleukin‐1β (IL‐1β), and IL‐6 which play crucial roles in occurrence and development of sepsis." (PMID 38455195, 2023). "PGE2 induces M2 macrophage polarization in vitro and its effects have been demonstrated in a mouse model of sepsis, whereby is responsible for increasing IL-10 and decreasing TNF-α and IL-6 expression in macrophages." (PMID 37185486, 2023). "During sepsis, IL-6 levels rise rapidly after TNF-α and IL-1 concentrations and play a vital role in the patient’s progression to multiorgan failure." (PMID 38275661, 2023). "Coagulation, complement, IL6–JAK–STAT3 signaling, inflammatory response and TNFα signaling via NFκB were considerably enriched in the patients with pediatric sepsis (P adjusted < 0.05)." (PMID 37115484, 2023). "TNF-α is often the main target in the treatment of various inflammatory diseases and plays a role in infectious disease and sepsis pathophysiology." (PMID 37626822, 2023). "IL-10 is also released into the circulation during human sepsis and controls the production of TNF, IL-1, and IL-8 in vitro." (PMID 37004108, 2023). "We next looked for evidence of acute systemic sepsis by measuring serum concentrations of the pro-inflammatory cytokines IL-6 and TNFα in mice." (PMID 37681974, 2023). "Shedding of the glycocalyx is largely mediated by matrix metalloproteinases (MMPs) which are upregulated in TNFα activated ECs23 and during sepsis, among other inflammatory conditions." (PMID 36934164, 2023). "Compared to the placebo group, sepsis patients in the clarithromycin group showed a decrease in serum IL-10 to TNF-α ratio and restoration of the balance between pro- and anti-inflammatory mediators." (PMID 38114466, 2023). "Namely, LPS-induced inflammation and/ or sepsis results in the activation of both TNF-α and IL-1β, but these cytokines initiate different pathways’ cascades that cooperate in the induced effect, even though they are distinctively different." (PMID 38136765, 2023). "The microvascular endothelium is activated in various disease states (e.g. severe sepsis) by the cytokine TNF-α, triggering the release of endothelial EVs into the bloodstream." (PMID 36961624, 2023). "In sepsis-induced kidney injury, many pro-inflammatory cytokines are released, mainly IL-1β, IL-6, and TNF-α." (PMID 36737765, 2023). "In light of this approach, a recent RCT in children with sepsis defined immunoparalysis treated with GM-CSF as an LPS-induced TNF production capacity < 200 pg/mL (NCT05266001)." (PMID 38057824, 2023). "TNF-α is a multifunctional proinflammatory cytokine that induces an inflammatory storm, and most of it is synthesised in the liver, leading to sepsis and liver damage." (PMID 37753078, 2023). "In contrast, LPS increased the supernatant IL-1β, IL-6, IL-8, IL-10, and TNF-α concentrations at 24 and 48 h better in patients with trauma than sepsis." (PMID 36615909, 2023).
Sepsis (continued). "Pro-inflammatory cytokines that are believed to be involved in excessive inflammation in sepsis are TNFα (tumor necrosis factor-alpha), IL-1β (interleukin-1β), IL-12 (interleukin-12), and IL-18 (interleukin-18)." (PMID 37627293, 2023). "In sepsis, the endothelium is activated directly by PAMPs or indirectly by NETs and pro-inflammatory cytokines, including TNF-α, IL-6, and IL-1." (PMID 37569751, 2023). "In this study, we found that PT pretreatment significantly reduced the levels of serum TNF-α, IL-1β, and IL-6 induced by sepsis." (PMID 38152336, 2023). "We observed a sustained neuroinflammatory process in these surviving animals, and 13 days after sepsis induction, we detected increased IL-1β and TNF-α levels in both structures (hippocampus and cerebral cortex) of septic-surviving WT mice." (PMID 37153798, 2023). "We observed that sepsis increased circulating inflammation markers, such as TNFα and IL-1β, as well as mitochondrial oxidative stress in heart tissue." (PMID 37147703, 2023). "Consistently, the ELISAs of TNF-α, IL-1β and IL-6 showed that the serum TNF-α, IL-1β and IL-6 levels in the sepsis group were higher than those in the control group." (PMID 36544058, 2023). "In obese patients with sepsis, TNF-α mRNA levels, plasma thiobarbituric acid reactive substances, and protein carbonates are increased in visceral AT, while total plasma antioxidant capacity is decreased." (PMID 38027963, 2023). "In contrast to substantial literature examining mHLA-DR prognostic significance in adult sepsis, there are fewer reports on TNF-α, and most are in small groups of children." (PMID 36825018, 2023). "These macrophages are responsible for reducing cytokine levels, including IFNγ, TNF, IL-6, and IL-10, in patients with sepsis." (PMID 38193079, 2023). "Studies on sepsis have shown that TNF-α upregulates the expression of NLRP3 through the NF-κB signaling pathway, induces polarization of macrophages to M1 macrophages and causes pyroptosis of lung macrophages, leading to histological lesions." (PMID 37686375, 2023). "As mesenchymal stem cell (MSC) secretome is known to have immunomodulatory effects, we aim to assess the role of MSC secretome in the inflammatory mediators (NF-κB p65 and p50, TNF-α, IL-10) and the survival rate of a rat model of sepsis." (PMID 37626822, 2023). "Inflammatory cytokines such as IL-6, TNF-α, IFN-γ, and IL-1β, whose expression levels increase at the onset of sepsis, cause acute muscle wasting." (PMID 36902469, 2023). "Correspondingly, in an ex-vivo study using blood samples from patients with sepsis or septic shock (n=20), mHLA-DR expression correlated with TNF-α response." (PMID 36825018, 2023). "For example, the lncRNA THRIL is upregulated in human bronchial epithelial cells in sepsis and sponges miR-19a, which resulted in increased expression of TNF-α and promoted lung cell apoptosis." (PMID 36941625, 2023). "The incidence of severe sepsis and the concentrations of inflammatory factors (CRP, PCT, TNF-α) in sepsis caused by G (−) bacteria were higher than those caused by G (+) bacteria." (PMID 38037118, 2023). "Since sepsis is usually accompanied by VEC dysfunction, and proinflammatory cytokines IL-1β, IL-6 and TNF-α are important in the occurrence and development of sepsis, we first examined if E2 can affect release of inflammatory cytokines from HUVEC." (PMID 37265700, 2023). "Prior research has demonstrated that sepsis can lead to the buildup of proinflammatory cytokines, such as tumor necrosis factor-alpha (TNF-α) and interleukin-1β (IL-1β), within the pulmonary system." (PMID 37970921, 2023). "The mice 12 h after CLP-induced sepsis had marked elevations in TNF-α, IL-6, and INF-γ levels in serum." (PMID 37372931, 2023). "The potential of TNF-α, IL-1β, and IL-6 as biomarkers for patients with sepsis has been proposed, and the combined test of the three has an excellent predictive value in individuals with sepsis-induced cardiomyopathy." (PMID 37650558, 2023).
Sepsis (continued). "Recently, it has been found that during sepsis there is accelerated megakaryocyte maturation, triggered by PAMPs, DAMPs, TNF-α, or other cytokines." (PMID 37081895, 2023). "Interleukin (IL) and tumor necrosis factor-α (TNF-α) are pro-inflammatory cytokines that are released in large quantities during sepsis and further contribute to numerous cell death and organ malfunction." (PMID 37529169, 2023). "GEE results revealed that zone 1 ROP, stage 3 ROP, older baseline PMA, RDS, NEC, and sepsis were associated with increases or decreases in the serum levels of GM-CSF, IL-5, IL-15, ICAM-1, TNF-α, and TNFR-2 in premature infants." (PMID 38259597, 2023). "In our sepsis model, the serum levels of three major inflammatory cytokines, TNF-α, IL-6, and IL-1β, were drastically elevated at 12 h of induction." (PMID 36675101, 2023). "As expected, the levels inflammatory cytokines TNF-α, IL-1β, IL-6 were increased in serum and lung in sepsis mice compared with control group." (PMID 37494665, 2023). "CD14 has recently been shown to be an important, highly cell-specific mediator of TNF response in a mouse sepsis model." (PMID 38065997, 2023). "In our study, EA reduced the W/D and lung tissue damage in sepsis mice, down-regulated the expression of serum inflammatory cytokines TNF-α and IL-6, and increased the survival rate of sepsis mice." (PMID 37635258, 2023). "S100A8/9, IL-1, IL-4, and tumor necrosis factor have all been identified in previous research as markers of sepsis-related brain damage in plasma." (PMID 37901226, 2023). "The level of TNF-α in the body increases in response to various inflammatory triggers, such as autoimmune diseases, trauma, and infection/sepsis." (PMID 37108065, 2023). "The administration of MSC secretome gave an immunoregulatory effect in the form of a decreased expression of NF-κB p65 and p50, as well as a decrease in the serum TNF-α level, and an increased serum IL-10 level in rat model of sepsis." (PMID 37626822, 2023). "In other murine models and clinical cases of sepsis, the serum upregulation of IL-6, TNFα, and HMGB1 was observed." (PMID 37569277, 2023). "Some authors support that pro-inflammatory immune response in sepsis, with particularly high levels of expression of IL-6 and tumor necrosis factor (TNF), impaired acquired immunity (lymphopenia) and induced an uncontrolled innate response." (PMID 37935890, 2023). "TNF, a potent proinflammatory cytokine promoting various diseases, including hyper-inflammatory diseases (e.g., arthritis, sepsis, pneumonia), is primarily produced from immune cells like macrophages." (PMID 37280310, 2023). "TNFα is known to profoundly modulate genes relevant for bile acid metabolism in sepsis-induced cholestasis." (PMID 37280200, 2023). "A higher level of IL-6 on day 7 and a lower level of inflammation (both IL-6 and TNF-α) on day 9 were observed in the Sepsis + DEX group than in the sepsis group." (PMID 37114154, 2023). "During sepsis, immune cell-derived cytokines such as TNF-α, IL-IL-1-β, IL-6, and IL-10 activate the HPA axis." (PMID 37600769, 2023). "HBO2 treatment has been shown to reduce proinflammatory cytokines such as IL-1, IL-6, and TNF-α both in vitro and in vivo, and HBO2 treatment was associated with a decrease in IL-6 and G-CSF in plasma from Group A-Streptococcus NSTI sepsis patients." (PMID 37627293, 2023). "In mouse models of sepsis, OI has been shown to prolong survival and decrease IL-1β and TNF release in response to LPS challenge." (PMID 37730914, 2023). "We found that Daph obviously protected animals from mortality, reduced the LPS-induced alveolar edema and inflammation cells infiltration in sepsis mice, and suppressed the production of pro-inflammatory factors including IL-1β, IL-18, IL-6, TNF-α and iNOS." (PMID 36998049, 2023). "These factors can contribute to multi-organ failure, highlighting the central role of TNF-α in the pathophysiology of sepsis." (PMID 38313162, 2023).